GLIPR1 (GLI pathogenesis related 1)
Synonyms: GLIPR; RTVP1; CRISP7
Tractability: Antibody: its Gene Ontology location is reachable by antibodies, with high confidence; UniProt predicts a signal peptide or a membrane-spanning region.
Gene: Protein-coding gene on chromosome 12 (75,480,753 to 75,503,863, forward strand). Ensembl gene ENSG00000139278.
Subcellular location: Membrane
Subcellular location (Human Protein Atlas): Vesicles; Nucleoplasm
Pathways (Reactome):
Immune System: Neutrophil degranulation
Metabolism: PPARA activates gene expression
Gene Ontology:
Molecular function: protein binding
Cellular component: membrane; azurophil granule membrane; plasma membrane; extracellular region
Genetic constraint (gnomAD): Loss-of-function variants: 12 observed, 14.83 expected, observed/expected ratio (o/e) 0.81, 90% interval 0.52 to 1.31. The upper end of that interval is the gene's LOEUF score, 1.31, which puts it in group 5 of 6, group 1 being the genes least tolerant of losing a copy. Missense variants: 140 observed, 171.01 expected, observed/expected ratio (o/e) 0.82, 90% interval 0.71 to 0.94. Synonymous variants: 55 observed, 61.85 expected, observed/expected ratio (o/e) 0.89, 90% interval 0.71 to 1.11.
Homologues: Orthologues: chimpanzee GLIPR1 (100% identical), rabbit GLIPR1 (82% identical), guinea pig GLIPR1 (78% identical), pig GLIPR1 (75% identical), dog GLIPR1 (70% identical), mouse Glipr1 (69% identical), rat Glipr1 (64% identical), Caenorhabditis elegans scl-15 (23% identical), Caenorhabditis elegans scl-2 (22% identical), Caenorhabditis elegans scl-20 (22% identical), Caenorhabditis elegans scl-7 (22% identical), Caenorhabditis elegans scl-5 (21% identical), and 39 more. Paralogues in human: GLIPR1L2 (38% identical), GLIPR1L1 (36% identical), CRISPLD2 (32% identical), CRISPLD1 (31% identical), CRISP3 (28% identical), PI15 (27% identical), CRISP1 (27% identical), CRISP2 (26% identical), R3HDML (25% identical), CLEC18B (24% identical), CLEC18A (23% identical), CLEC18C (23% identical), and 1 more.
Diseases named in the same sentence as GLIPR1 in open-access papers:
GLIPR1 is named in the same sentence as 46 diseases in open-access papers, as found by Europe PMC text mining. Sharing a sentence is not in itself a finding about the gene and the disease. The quoted sentences say what the papers report.
glioma (30 papers, 2005 to 2024). A benign or malignant brain and spinal cord tumor that arises from glial cells (astrocytes, oligodendrocytes, ependymal cells). "At the same time that mechanisms underlying GliPR1 regulation of glioma cell migration and invasion were being elucidated, we were interested to assess its value as a therapeutic target in glioblastoma." (PMID 33856615, 2021). "We conducted in vitro and in vivo experiments to investigate whether RNA interference targeting GliPR1, via transduction of small-hairpin RNA (shRNA) sequences, causes knockdown of its gene and protein expression and exerts anti-glioma effects." (PMID 33856615, 2021). "Cultured ELISPOT assays clearly confirmed responses against individual minigenes from two pools targeted by T cells from subject ND2, one derived from epithelial adhesion molecule, EpCAM in pool #308, and another encoding a portion of glioma pathogenesis associated protein, GLIPR1 in pool #85." (PMID 22253836, 2012). "GLIPR1 is identified as an oncoprotein in some cancer types including gliomas, melanoma cancers, breast cancers, and Wilms tumors, but as a tumor suppressor in some other cancers, like bladder cancers, prostate cancers, thyroid cancers, and lung cancers." (PMID 38368374, 2024). "GLIPR1 is very well studied in cancer and has been found to regulate migration and invasion of glioma cells." (PMID 36412091, 2022). "GliPR1 knockdown in glioma cells decreased cellular proliferation, decreased clonogenic survival, and induced apoptosis in vitro, and reduced glioblastoma tumor growth and prolonged survival in vivo." (PMID 33856615, 2021). "In contrast, GLIPR1 overexpression in glioma and osteosarcoma cells leads to an increase in the proliferation, survival, invasion, migration, and anchorage-independent growth." (PMID 34142021, 2021). "Our in vivo findings provide evidence that GliPR1 knockdown by RNA interference in glioma cells translates into reduced glioblastoma tumor growth and prolonged survival in tumor-bearing nude mice." (PMID 33856615, 2021). "These in vitro findings are in line with those from another research group, who reported decreased cellular proliferation and induced apoptosis in glioma cells following GliPR1 knockdown mediated by transfection of a small interfering (si)RNA against GliPR1." (PMID 33856615, 2021). "Second, transduction of three human glioblastoma cell lines with the same two shGliPR1s via a constitutive retroviral-shRNA vector enabled establishment of polyclonal glioma cells exhibiting stable knockdown of GliPR1 gene and protein expression." (PMID 33856615, 2021). "In another study, the siRNA-mediated knockdown of GLIPR1 expression induced a reduction in the number of melanomas, glioma cell invasion and proliferation." (PMID 34142021, 2021). "Our in vitro findings in glioma cells provide evidence of anti-glioma effects of GliPR1 knockdown by RNA interference." (PMID 33856615, 2021). "The overexpression of GLIPR1 increases glioma cell proliferation, whereas the downregulation of GLIPR1 decreases the proliferation of glioma and melanoma cells." (PMID 28771580, 2017). "It has been found that DNA hypomethylation of the GLIPR1 gene promoter led to its overexpression in glioma and wilms tumors, whereas hypermethylation of the GLIPR1 gene promoter led to the downregulation of its mRNA expression in prostate cancer." (PMID 28771580, 2017). "The overexpression of GLIPR1 has been demonstrated to induce apoptosis in prostate cancer cells; however, overexpression of GLIPR1 increased glioma cell proliferation and downregulation of GLIPR1 decreased the proliferation of glioma and melanoma cells." (PMID 28771580, 2017). "Our results are consistent with studies in glioma and melanoma cells, in which GLIPR1 promotes cell proliferation." (PMID 28771580, 2017). "GLIPR1 is highly expressed in gliomas and astrocytic brain malignancies, and its expression level is correlated with the degree of malignancy of astrocytic tumors." (PMID 26988096, 2016).
glioma (continued). "GLIPR1 overexpression increased cell proliferation, survival, invasion, migration and anchorage-independent growth of glioma cells." (PMID 26988096, 2016). "Related to testis-specific, vespid and pathogenesis protein 1 (RTVP-1) was originally cloned from human GBM cell lines by two groups and was termed glioma pathogenesis-related protein - GLIPR1 or RTVP-1." (PMID 26267319, 2015). "We used glioma cell lines in which GLIPR1 had previously been shown to modulate invasive behavior as positive controls to compare with melanoma cell lines in our in vitro invasion assays." (PMID 24010123, 2013). "GLI pathogenesis-related 1 (GLIPR1) was previously identified as an epigenetically regulated tumor suppressor in prostate cancer and, conversely, an oncoprotein in glioma." (PMID 24010123, 2013). "Having confirmed variable expression of GLIPR1, we then chose to investigate the relationship between GLIPR1 abundance and invasion in melanoma and glioma cells." (PMID 24010123, 2013). "SNB75 glioma cells, with the highest pre-knockdown migration rate, showed about a 50% decrease in cell migration 24 h after GLIPR1 knockdown." (PMID 24010123, 2013). "Using RT-qPCR and western blots we found variable expression of GLIPR1 mRNA and protein in different metastatic melanoma cell lines with two melanoma cell lines having similar levels to glioma cell lines previously reported as having high GLIPR1 expression." (PMID 24010123, 2013). "SNB75 cells previously shown to have elevated GLIPR1 expression, showed the highest expression levels within the melanoma and glioma cells tested, with 110-fold higher abundance relative to NZM15 cells." (PMID 24010123, 2013). "In contrast, GLIPR1 is up-regulated in glioma and Wilms’ tumor compared to normal tissue, and has recently been shown to be differentially expressed in ovarian cancer cell lines." (PMID 24010123, 2013). "In contrast to its oncogenic effect in glioma, where GLIPR1 regulates proliferation, migration and survival of glioma cells, it acts as a tumour suppressor in prostate cancer." (PMID 20565761, 2010). "As an oncogene, GLIPR1 is necessary for stemness of glioma stem cells." (PMID 38368374, 2024). "GLIPR1 could promote migration and invasion of glioma and epithelial-mesenchymal transition by mediating signal transducer and activator of transcription 3 (STAT3) pathway and IL-6." (PMID 38368374, 2024). "In glioma cells, GLIPR1 overexpression reduced c-Jun N-terminal kinase (JNK) phosphorylation and induced Bcl-2 expression, thus increasing cell survival and glioma cells’ protective effect against apoptotic stimuli such as Fas ligation, chemotherapy, and radiation treatment." (PMID 34142021, 2021). "Taken together with other laboratory findings, our observed anti-glioma effects of GliPR1 knockdown support that GliPR1 may have potential value as a therapeutic target for this aggressive brain tumor with a poor prognosis." (PMID 33856615, 2021). "Initially identified as a tumor-suppressor gene with apoptosis-inducing activities in prostate cancer, GLIPR1 pleiotropic effects have been reported to be highly expressed and upregulated, and it acts as an oncogene specifically in glioblastomas and gliomas, thus promoting cell proliferation." (PMID 34142021, 2021). "To limit any positional effects of provirus, we then established polyclonal glioma cells with stable GliPR1 knockdown, by transducing three human glioblastoma cell lines (U87-MG, A172, U343-MG) with each of GliPR1 sh#301 and GliPR1 sh#258 using a constitutive retroviral-shRNA vector." (PMID 33856615, 2021). "In conclusion, we found that GliPR1 knockdown in glioma cells by RNA interference decreased cellular proliferation, decreased clonogenic survival, and induced apoptosis in vitro, and reduced glioblastoma tumor growth and prolonged survival in vivo in tumor-bearing nude mice." (PMID 33856615, 2021). "We investigated whether GliPR1 knockdown in glioma cells by RNA interference exerts anti-glioma effects." (PMID 33856615, 2021).
glioma (continued). "The GLIPR1 gene has been identified in different forms of human cancers, including prostate, lung, ovarian, Wilms’ tumor, acute myeloid leukemia, and in the most aggressive types, brain cancer, glioblastoma multiforme/astrocytoma, and within glioma cell lines." (PMID 34142021, 2021). "First, transduction of a human glioblastoma cell line with each of two shGliPR1s (sh#301 and sh#258) via a lentiviral “all-in-one” TetOn vector enabled establishment of glioma cell clones exhibiting stringent doxycycline-dependent knockdown of GliPR1 gene and protein expression." (PMID 33856615, 2021). "GLIPR1L1 participates in the encoding of the glioma pathogenesis-related protein (GLIPR1), a member of the CAP superfamily, and could promote the proliferation, survival, and invasion of glioma cells and inhibit apoptosis." (PMID 33230136, 2020). "GLIPR1 knockdown caused a modest but reproducible decrease in proliferation in both melanoma and glioma cells, suggesting that GLIPR1 may play a role in cell growth at some level." (PMID 24010123, 2013). "GLIPR1 transcript and protein have been reported in various tissues including heart, lung, liver, spleen, skin, colon, pancreas, lymphocytes, muscle, bone marrow, placenta, adrenal gland, prostate, glioma, and prostate cancer." (PMID 24010123, 2013). "GLIPR1 has also been shown to regulate growth, survival, and invasion of glioma cells." (PMID 24010123, 2013). "Interestingly, a study in metastatic melanoma cell lines found an association between decreasing promoter methylation and increasing GliPR1 gene expression, and siRNA-mediated GliPR1 knockdown in melanoma cells decreased cellular proliferation, similar to glioma cells." (PMID 33856615, 2021). "GLIPR1 is also called RTVP1, belonging to the GAP protein superfamily, found early in human gliomas as a proto-oncogene." (PMID 36011359, 2022). "Related to testis-specific, vespid and pathogenesis protein 1 (RTVP-1) was cloned from human GBM cell lines by and was termed glioma pathogenesis-related protein (GLIPR1) or RTVP-1." (PMID 26305187, 2015). "siRNA-mediated knockdown of GLIPR1 resulted in a 10–22% decrease in proliferation in melanoma cells compared to 31 and 25% decrease for U251 and SNB75 glioma cells respectively, 4 days after transfection." (PMID 24010123, 2013). "siRNA-mediated knockdown of GLIPR1 resulted in a significant decrease in the number of melanoma and glioma cells migrating across the membrane relative to non-targeting controls." (PMID 24010123, 2013). "Overexpression of GLIPR1 has previously been shown to increase invasion of several glioma cell lines, and is consistent with our findings in melanoma cells suggesting GLIPR1 acts as an oncoprotein rather than a tumor suppressor in melanoma." (PMID 24010123, 2013). "However, unlike glioma, there was no obvious relationship between GLIPR1 positivity and melanoma progression." (PMID 24010123, 2013).
prostate carcinoma (21 papers, 2010 to 2025). A carcinoma that arises from epithelial cells of the prostate gland. "Reduced GLIPR1 expression in prostate cancer cells was shown to be primarily caused by aberrant DNA hypermethylation." (PMID 31995627, 2020). "It was previously shown that MYC overexpression and loss of Glipr1 expression co-operate to promote prostate cancer development in vivo." (PMID 31995627, 2020). "Decreased expression of GLIPR1 gene is associated with prostate cancer and Leprel1 functions as a suppressor of cell proliferation and their down-regulation or silencing was observed in cancers." (PMID 27480244, 2016). "In prostate cancer, increased expression of GLIPR1 is associated with apoptosis induction." (PMID 26302043, 2015). "In prostate cancer, systemic administration of a truncated recombinant form (GLIPR1-ΔTM) has demonstrated potent anti-tumor effects, including induction of ROS-mediated apoptosis and suppression of oncogenic c-Myc signaling." (PMID 41208460, 2025). "Downregulation of GLIPR1 in prostate cancer and other malignant cell lines has been observed, largely in part to the methylation of the human GLIPR1 promoter." (PMID 34142021, 2021). "Originally identified as a tumor-suppressor gene with apoptosis-inducing activities in prostate cancer, GLIPR1 has been reported to be upregulated in glioblastomas, enhancing cell proliferation." (PMID 34142021, 2021). "Downregulation of c-Myc protein and CK1a-mediated targeted destruction of c-Myc and b-catenin in prostate cancer cell lines contributes to apoptosis induction by GLIPR1." (PMID 34142021, 2021). "For example, in prostate cancers, glioma pathogenesis-related protein 1 (GLIPR1) mediates the translocation of CK1α to the nucleus, leading to the phosphorylation and degradation of C-Myc and inhibition of Wnt activity." (PMID 32824859, 2020). "In contrast, glioma pathogenesis-related protein 1 (GLIPR1) is down-regulated in prostate cancer, while forced GLIPR1 overexpression is pro-apoptotic in prostate cancer cells and is suggested as a prostate-cancer therapy." (PMID 32906672, 2020). "The same study also found that GLIPR1 overexpression in prostate cancer cell lines led to a reduction in MYC expression due to GLIPR1 directly decreasing MYC transcription as well as promoting the ubiquitination and degradation of MYC protein." (PMID 31995627, 2020). "Given that enforced GLIPR1 expression in prostate cancer cells caused a reduction in MYC mRNA levels, the effect of Glipr1 re-expression on the expression levels of Myc in 5TGM1 cells was assessed." (PMID 31995627, 2020). "GLIPR1 has been found to mediate its tumour suppressor effects in prostate cancer cells through several different mechanisms." (PMID 31995627, 2020). "A novel GLIPR1-modified tumor cell vaccine also showed significant antitumor activity in a mouse model of recurrent prostate cancer." (PMID 26988096, 2016). "Overexpression of GLIPR1 induced apoptosis and/or mitotic catastrophe (MC) in prostate cancer cells." (PMID 26988096, 2016). "In contrast, GLIPR1 expression was down-regulated in prostate cancer and functions as a tumor-suppressor gene in prostate cancer." (PMID 26988096, 2016). "GLIPR1 was shown to induce apoptosis in prostate cancer, and to promote MYC ubiquitination and degradation leading to suppression of cancer development." (PMID 23702334, 2013). "Epigenetics studies have shown that hypermethylation in the promoter region of GLIPR1 is responsible for the down-regulation of GLIPR1 in prostate cancer." (PMID 24010123, 2013). "GLI pathogenesis-related 1 (GLIPR1) has been reported to act as a tumor suppressor gene that is down-regulated in prostate cancer (1–, 3)." (PMID 24010123, 2013).